PGF (placental growth factor)
Diseases named in the same sentence as PGF in open-access papers (continued):
Sharing a sentence is not in itself a finding about the gene and the disease.
tumor (continued). "Studies have found that placental growth factor (PLGF), which is highly expressed in small cell lung cancer (SCLC), decomposes TJs by activating the VEGFR1–ROCK–ERK1/2 axis to promote tumor cell transendothelial migration." (PMID 41583906, 2026). "FLT1 is also a receptor for placental growth factor (PGF), which positively regulates cell proliferation and tumor growth." (PMID 41020821, 2025). "Placental Growth Factor (PGF) is a member of the vascular endothelial growth factor (VEGF) family and is primarily involved in angiogenesis, inflammation, and tumor progression." (PMID 40558258, 2025). "In the high-risk state, the expression levels of VEGFA were significantly increased in Macrophages, Mast cells, Monocytes and tumor cells; FLT1 and KDR were significantly increased in Endothelial; and PGF was significantly increased in Mesangial." (PMID 40563096, 2025). "Overexpression of placental growth factor (PGF) and VEGFA, as members of the VEGF family proteins, correlates with tumor growth and progression in various cancers." (PMID 38339062, 2024). "TIMP1, PGF, FSTL3, SNAI1, and FOXC1 were highly expressed in CAFs with high stemness scores in the tumor intestinal tissues." (PMID 37017587, 2023). "Polymeric NPs were developed to deliver vascular endothelial growth factor (VEGF) siRNA and placental growth factor signaling (PIGF) siRNA to both tumor cells and TAMs, leading to suppressed tumor growth and metastasis." (PMID 36810108, 2023). "Proangiogenic substances like Vascular Endothelial Growth Factor (VEGF), basic fibroblast growth factor (bFGF), placental growth factor (PGF), and angiopoietin are released by tumor cells to initiate angiogenesis." (PMID 37056346, 2023). "For example, tumor growth and mesenteric metastases from orthotopic transplants were increased by HFD-induced placental growth factor (PIGF)/VEGFR-1 signaling that repolarized macrophages towards a pro-tumorigenic phenotype (M2) in the tumor microenvironment." (PMID 37648285, 2023). "The members of the VEGF family, which includes VEGF-A, VEGF-B, VEGF-C, VEGF-D, and placental growth factor (PLGF), represent the most well-defined pro-angiogenic factors known to promote tumor angiogenesis." (PMID 36901858, 2023). "The VEGF family, which presently consists of placental growth factor and VEGF-A to VEGF-D, is involved in a variety of human tumor types." (PMID 38069386, 2023). "NK cells isolated from lung tumors (as well as matched blood and lung margin) have also been shown to produce tumor-promoting angiogenic factors, including vascular endothelial growth factor (VEGF), placental growth factor (PlGF) and IL-8." (PMID 35844626, 2022). "VEGFA belongs to the VEGF family (vascular endothelial growth factor; VEGFA, VEGFB, VEGFC, VEGFD, placenta growth factor [PGF]) and represents the best characteristics for angiogenesis to promote tumor growth and systemic metastasis." (PMID 35203290, 2022). "For example, it has been demonstrated that primary tumour-secreted factors, such as the vascular endothelial growth factor A (VEGF-A) and placental growth factor (PGF), can mobilise hematopoietic cells in lungs before the arrival of metastatic cancer cells." (PMID 36612237, 2022). "It is considered that tumor cells release VEGF and placental growth factor prior to invasion and metastasis to promote tumor metastasis to the target organs." (PMID 35773697, 2022). "For instance, Δ9-THC reduced both angiopoietin-2 (Ang-2) and placental growth factor (PIGF) production in tumor cells, whose effect in neoplasms and chronic myeloproliferative diseases is well known." (PMID 34202812, 2021). "Placental growth factor (PlGF), as a member of the VEGF family that induces an angiogenic phenotype, directly interacts with VEGFR1 to stimulate tumor angiogenesis and promote macrophage repolarization into the M2-like phenotype, facilitating immune escape." (PMID 34294146, 2021).
tumor (continued). "It has been reported that many tumor angiogenic factors contribute to the immunosuppressive TME, including vascular endothelial growth factors, angiopoietin 2, placental growth factor, and transforming growth factor-β." (PMID 34294146, 2021). "The initial step of premetastatic niche formation in specific organ sites is mediated by tumor‐derived soluble factors such as TNF‐α, TGF‐β, CXCL12, placental growth factor and VEGF‐A49 as well as by tumor‐derived exosomes." (PMID 32761606, 2021). "In this study, from the perspective of tumor immunity, we identified MMP9, IGF1, CXCL12 and PGF as prognostic differentially expressed IRGs for the first time." (PMID 32675942, 2020). "VEGF protein family consists of VEGF A, B, C, D, F, placental growth factor (PIGF), and their receptors VEGFR-1, 2, 3, among which VEGF-A (or VEGF) and VEGFR-2 are widely accepted as mostly responsible for tumor development." (PMID 30702616, 2019). "In animal studies, scientists showed the involvement of primary tumor tissue in developing bone metastasis by increasing activity of vascular endothelial growth factor (VEGF) and placental growth factor (PGF)." (PMID 31731466, 2019). "PGF is a member of the vascular epidermal growth factor (VEGF) family, with identified roles in tumor angiogenesis and inflammatory pathways." (PMID 30754719, 2019). "In this cross-sectional study, we found that circulating and tumor tissue expression of NRP-1 and circulating placental growth factor (PlGF) increase in advanced nodal and metastatic breast cancer compared with locally advanced disease." (PMID 28607365, 2017). "Macrophages are important for this angiogenic switch in tumours particularly through production of vascular-endothelial growth factor A (VEGF-A) and placental growth factor (PlGF)." (PMID 28210073, 2017). "Several key regulators of tumor angiogenesis have been identified, including vascular endothelial growth factor (VEGF), placental growth factor (PLGF), and angiopoietins-1 and 2 (Ang1, Ang2)." (PMID 27330805, 2016). "MDSCs reportedly promote tumor angiogenesis and growth through secretion of various cytokines, including VEGF and placental growth factor (PlGF), among others." (PMID 27391260, 2016). "VEGF–VEGFR signalling plays an important role in angiogenesis and vasculogenesis, VEGFR1 is expressed on tumour cells and binds to VEGFR-A, VEGFR-B, and placental growth factor." (PMID 27488093, 2016). "The inflammatory contexts can promote tumor growth through the production of cytokines such as IL-6, IL-1, or TNF-a and angiogenic molecules such as VEGFA, placental growth factor (PlGF), or transforming growth factor-b (TGF-b)." (PMID 27006653, 2016). "Tumor cells release increasing amounts of VEGF and placental growth factor (PlGF) in response to Epo." (PMID 26919105, 2016). "The VEGF-signaling pathway is the key regulator of tumor growth and metastasis and consists of five ligands (VEGFA-D and placental growth factor (PlGF)) and three RTKs (VEGFR1, VEGFR2, VEGFR3)." (PMID 25197551, 2014). "Placental growth factor (PlGF), a homolog of vascular endothelial growth factor (VEGF), exerts pleiotropic functions in cancer by affecting tumor cells as well as endothelial and inflammatory cells." (PMID 23232836, 2013). "Placental growth factor (PlGF), a member of the VEGF family, can bind VEGFR1 and neuropilins expressed on ECs, macrophages and tumor cells." (PMID 24314323, 2013). "In the present study, the expression patterns of a number of tumor-related classical genes (eg, VEGF, PGF, FGF18, AKT, E2F1, ATF5) within our microarray dataset were detected as predicted." (PMID 22962576, 2012). "Placental growth factor (PlGF) binds exclusively to VEGFR-1, and targeting of PlGF inhibits angiogenesis in various pathological settings, including tumor growth." (PMID 21124841, 2010). "Placental growth factor, a VEGF-related factor, contributes to tumour angiogenesis by providing increased survival function to ECs." (PMID 17505508, 2007).
tumor (continued). "TAMs involve in tumor angiogenesis by secreting several pro-angiogenic cytokines, including VEGFA, platelet-derived growth factor β (PDGF-β), angiogenin, placental growth factor (PlGF), TGF-β, and MMPs." (PMID 40443670, 2025). "Macrophages are the primary producers of numerous molecules that facilitate tumor angiogenesis, such as VEGFA, CXCL8 (chemokine (C-X-C motif) ligand 8), PlGF (placental growth factor), IL-1β (interleukin-1 beta), IL-6 (interleukin-6), TNF (tumor necrosis factor), MMPs, and cathepsins." (PMID 40940953, 2025). "Furthermore, bidirectional crosstalk between TAMs and NSCLC cells via placental growth factor (PLGF)/Flt-1 and TGF-β signaling intensifies vascular sprouting and tumor progression." (PMID 41058699, 2025). "Placental growth factor (PlGF) is a cytokine VEGF homolog that activates vessel formation and various types of cells, such as myeloids and stromal malignancies, in addition to activating tumor cells, while their inhibition improves cancer treatment." (PMID 38803919, 2024). "MiR-342-5p could target placental growth factor (PGF), which participates in the activation of the mitogen-activated protein kinase (MAPK) pathway that regulates carcinogenesis, tumor cell invasion, and metastasis." (PMID 39684711, 2024). "Furthermore, placental growth factor (PlGF) and VEGF-A expressed in CTCL skin were found to promote tumor growth via tumor vasculature formation." (PMID 39409988, 2024). "These infiltrated immune cells and solid tumor cells release tumor-progressing cytokines (IL-6, TNF-α, TGF-β), chemokines (CCL2, CCL5, CCL18, CXCL8, CXCL12), and growth factors (EGF, PGF, IGF-1, IGF-2, PDGF) that promote tumor microenvironment immunosuppressive." (PMID 37371075, 2023). "Moreover, tumor cells secrete a number of angiogenic growth factors, including VEGF, PDGF, placental growth factor (PlGF) and TGF-β1, to fulfill their need for high oxygen and nutrient supply." (PMID 36831649, 2023). "Moreover, the expressions of TIMP1, PGF, FSTL3, SNAI1, and FOXC1 were significantly up‐regulated in the tumor tissues." (PMID 37017587, 2023). "Tumor cells release a high amount of VEGF and contribute to angiogenesis via the release of proangiogenic signaling molecules, such as placental growth factor (PGF), VEGF-C, VEGF-D, and PDGF-C." (PMID 36140392, 2022). "VEGF-A, VEGF-B, placental growth factor (PLGF), and other types of VEGF interact with their corresponding receptors, promoting vascular growth, changing substances through permeability, and inhibiting tumor development." (PMID 36064413, 2022). "Once in the tumor, TAMs secrete pro-angiogenic factors such as VEGF-A, TGF-β, fibroblast growth factor-2 (FGF-2), CCL18, semaphorin 4D (Sema4D), adrenomedullin (ADM), and placental growth factor (PlGF)." (PMID 33783686, 2021). "C57 cells caused approximately 60% reduction of tumor volume by inhibiting tumor vascularization as indicated by modified blood vessel morphology and downregulation of proangiogenic factors, including VEGF, placental growth factor, and angiopoietin-2, and inducing apoptosis." (PMID 34393784, 2021). "However, high expression of oncogenic factors including IGFBP2, PGF, and TGFB2 was found specifically in subset 4, suggesting a different functional role of fibroblasts in liver metastasis compared to the primary tumor." (PMID 34671197, 2021). "Placental growth factor (PlGF) is a cytokine VEGF homolog that stimulates angiogenesis and various types of cells, such as myeloids and stromals cancers, in addition to activating tumor cells, while their inhibition improves cancer treatment." (PMID 31921634, 2019). "Moreover, targeting placental growth factor (PlGF)/NRP1 with monoclonal antibodies induced a direct antitumor effect in MB, resulting in tumor regression, decrease of metastasis and increase of survival in mouse models." (PMID 29632646, 2018).
tumor (continued). "In addition, placental growth factor (a member in the VEGF family), secreted by glioma tumor cells appears to switch tumor-infiltrating B cells to Bregsand suppress the CD8+ T-cell response." (PMID 30619286, 2018). "Placental growth factor (PlGF) is a homolog of VEGF, but selectively signals through VEGFR-1, that is expressed by various cell types including endothelial cells, mural cells, macrophages, bone marrow progenitors and tumor cells." (PMID 23232836, 2013). "Excessive production of VEGF, PDGF, and placental growth factor (PlGF) by solid tumor cells can result in excessive angiogenesis, and dysregulation of growth-factor/RTK interactions on tumors and tumor vasculature can result in increased tumor growth and metastasis." (PMID 22382879, 2012). "Tumor stromal pathways are also in evidence with the common genes including; TLR4, TLR7, HLA-DRA, HLA-DQA1, CXCR4, FOS and TGFB2 (immune surveillance and chemokine pathways) and NF2, ITGA7, PGF, ITGA4, PDGFD and PARVA (focal adhesion)." (PMID 23226201, 2012). "Up-regulated genes such as COL1A1, COL1A2, PGF or TGFB1, suggested an important role of these compartment in blood vessel formation, angiogenesis, permeability and invasiveness, essential functions in tumour progression." (PMID 20735813, 2010). "Common up-regulation of genes such as COL1A1, COL1A2, PGF, LRRFIP1, TMEFF2 or TGFB1 suggested an important role of this pool of cells in blood vessel formation, angiogenesis, permeability and proliferation pathways, essentials functions in tumour progression." (PMID 20735813, 2010). "These HPCs and macrophages mobilize in response to growth factors produced by the primary tumor, such as vascular endothelial growth factor A (VEGFA), placental growth factor (PlGF) and transforming growth factor-beta (TGFb), where they establish a pre-metastatic niche." (PMID 19997510, 2009). "Neuropilin-1 (NRP1), a type I transmembrane glycoprotein, has emerged as a key player in tumor biology, with roles in angiogenesis and tumor progression through vascular endothelial growth factor (VEGF), transforming growth factor-beta (TGF-β), and placental growth factor (PlGF) signaling pathways." (PMID 40805120, 2025). "Placental growth factor (PlGF) is a member of the vascular endothelial growth factor (VEGF) family, which induces endothelial cell proliferation and migration, as well as anti-endothelial cell apoptosis, increases the expression of vascular permeability, and is often involved in tumor angiogenesis." (PMID 38920989, 2024). "We, therefore, hypothesize that PARPi treatment leads to increased PGF expression in tumors, which in turn facilitates pro-survival signaling in FLT1-proficient (but not FLT1-deficient) tumor cells and culminates in the development of PARPi resistance." (PMID 38956205, 2024). "Notably, a significant rapid rise in tumor- and metastases-promoting molecules such as matrix metalloproteinase-9 (MMP-9), interleukin-6 (IL-6), hepatocyte growth factor (HGF), and placental growth factor (PLGF) was observed immediately (2 h) after surgery." (PMID 39451257, 2024). "Furthermore, mCAFs were enriched in angiogenesis-related pathways that send multiple angiogenesis-related signals to blood ECs, including PGF, VEGFA, and PDGF, indicating that mCAFs are the key CAFs in promoting tumor angiogenesis and inducing tumor growth and metastasis in HPSCC in vivo." (PMID 37853464, 2023). "The vascular endothelial growth factor (VEGF) family, including VEGF; placental growth factor (PLGF); and their receptors Flt-1, sFlt-1, and KDR (also known as VEGFR-1, sVEGFR-1, and VEGFR-2, respectively), are the most important promoters of physiological and tumor angiogenesis." (PMID 35878392, 2022).
tumor (continued). "Tumor angiogenesis occurs under the influence of fibroblast growth factor (FGF), epidermal growth factor (EGF), vascular endothelial growth factor (VEGF), placental growth factor (PLGF),tumor necrosis factor-alpha (TNFa), platelet-derived growth factor (PDGF) and angiogenin (Ang)." (PMID 35717207, 2022). "Important proangiogenic factors that are known to be involved in tumor angiogenesis include proteins of the vascular endothelial growth factor (VEGF) family, the platelet-derived growth factor (PDGF) family, the fibroblast growth factor (FGF) family, and placental growth factor (PlGF)." (PMID 30373628, 2018). "SL exposure also induced changes in the expression of genes involved in metabolic functions in tumor and stem cells (ALDH1B1, ABCB1, SLC3A2, SLC44A2, SLC31A2, SLC7A11, CYP24A1, PTGS2/COX2, PPRC1), cytokines (CCL3L3, GDF15) and growth and differentiation factors (PGF, TGFBR11 and FOXD1)." (PMID 24742967, 2014). "The importance of FLT1, PGF, VEGFA and VEGFB expression and their functions in MLS/RCLS tumor development remain unclear but our results point out this receptor/ligand system as operational in MLS/RCLS and as such a potential target for intervention in this tumor type." (PMID 20515481, 2010). "Moreover, there are many growth factors involved in tumor angiogenesis, such as vascular endothelial growth factor (VEGF), epidermal growth factor (EGF), angiogenin (Ang), fibroblast growth factor (FGF), platelet-derived growth factor (PDGF), TNF-α and placental growth factor (PLGF)." (PMID 38298540, 2023). "The possible mechanism is that angiogenesis in the tumor may be driven by additional factors, such as fibroblast growth factor 1 (FGF-1), FGF-2, transforming growth factor-β (TGF-β), platelet-derived endothelial cell growth factor (PD-ECGF), and placental growth factor (PIGF)." (PMID 23799045, 2013). "Level of circulating VEGF was independent of the tumor size and serum concentrations of two angiogenic factors, FGF2 and placental growth factor (PGF) were not different in metastatic vs. non-metastatic stage patients." (PMID 32326444, 2020). "We found that VEGF-A, -B, -C, -D, placental growth factor (PlGF), VEGFR-1, VEGFR-2, and VEGFR-3 were higher in tumor tissues than non-tumor tissues." (PMID 30862805, 2019). "When seeking the VEGFR1 ligands responsible for this cascade, we found that VEGF-A, but not placental growth factor (PIGF), was expressed both in vivo and in vitro, at least in our tumor models." (PMID 29212030, 2017). "In contrast, HT-1080s secreted placental growth factor (PIGF), a potent tumor angiogenic factor not detected with fibroblasts." (PMID 23226527, 2012).